HMGB1 (high mobility group box 1)
Diseases named in the same sentence as HMGB1 in open-access papers (continued):
Sharing a sentence is not in itself a finding about the gene and the disease.
Sepsis (continued). "The efficacy of administering HMGB1 blockade after a delay of up to 24 hours following the initiation of experimental sepsis presents a distinctive temporal window that affords potential for rescuing individuals from fatal septic conditions." (PMID 38510969, 2024). "Recent studies reported that the inhibition of TN binding to the target proteins, HMGB1 and plasminogen, are effective to suppress lethal sepsis and colon cancer proliferation, respectively." (PMID 38187250, 2024). "Eventually, lactylation and acetylation of HMGB1 lead to its exosomal secretion in macrophages, contributing to endothelial barrier dysfunction and vascular permeability which exacerbates sepsis progression." (PMID 39468303, 2024). "Studies along these lines have shown that for hepatocytes, HMGB1 attributes to alcoholic liver injury, sepsis, hepatocellular carcinoma, and fibrosis." (PMID 39682695, 2024). "Lactate promotes macrophage HMGB1 lactylation, acetylation, and exosomal release in polymicrobial sepsis." (PMID 38481182, 2024). "The administration of a monoclonal anti-HMGB1 antibody after sepsis onset in mice partially restored EPO signaling in vivo." (PMID 39591250, 2024). "In conclusion, our findings indicate that CGK012 treatment in mice with CLP-induced sepsis diminished HMGB1 release and increased the survival rate, suggesting its potential as a pharmaceutical intervention for sepsis." (PMID 38474222, 2024). "The present study established a murine model of sepsis and demonstrated that HMGB1 blockade effectively mitigates ferroptosis and oxidative stress while concurrently activating the Nrf2 signaling pathway." (PMID 38837857, 2024). "Circulating HMGB1, as an important damage-associated molecular pattern (DAMP) molecule, plays a crucial role in the progression and late-stage mortality of sepsis." (PMID 39234245, 2024). "In sepsis, the effect of HMGB1 in the complement system is particularly relevant due to its ability to exacerbate the inflammatory response and contribute to the development of a cytokine storm, a hallmark of severe sepsis and septic shock." (PMID 39445002, 2024). "An ALI model was established in C57BL/6 mice through CLP surgery to explore the impact of HMGB1 downregulation on ferroptosis and oxidative stress in sepsis‐induced ALI." (PMID 38837857, 2024). "Anti-HMGB1 polyclonal and monoclonal antibodies are utilized to antagonize extracellularly released HMGB1, especially in sepsis." (PMID 39682695, 2024). "Meanwhile, PL has been shown to effectively inhibit HMGB1 in different disease models, including cholestatic liver injury, hepatic ischemic re-injury, and sepsis." (PMID 38655086, 2024). "Diminished levels of HMGB1 following berberine treatment also correlated with diminished astrocyte activation in a model of sepsis." (PMID 38713518, 2024). "miR-22 alleviates sepsis-induced acute kidney injury via targeting the HMGB1/TLR4/NF-κB signaling pathway." (PMID 38443846, 2024). "Reducing lactate production or inhibiting GPR81 signaling in vivo was shown to decrease exosomal HMGB1 and improve survival in polymicrobia sepsis." (PMID 39850757, 2024). "Recent studies have shown that damage-associated molecular patterns (DAMPs) play a crucial role in sepsis, especially HMGB1 and histones." (PMID 39712008, 2024). "Peg13 mitigates the inflammatory response by reducing the release of proinflammatory cytokines HMGB1 and IL-6 in sepsis, presenting a potential therapeutic target for alleviating inflammation in sepsis treatment." (PMID 38856110, 2024). "We investigated the potential of CGK012 to attenuate the excessive permeability induced by HMGB1 and enhance survival rates in a mouse model of sepsis with reduced HMGB1 levels following lipopolysaccharide (LPS) treatment." (PMID 38474222, 2024). "Recent studies have highlighted that this cartridge also adsorbs DAMPs like HMGB1, histones, and S-100, but in this case, its role in improving the outcome of sepsis is also controversial." (PMID 38256033, 2024).
Sepsis (continued). "A variety of DAMPs are released during sepsis, including histones, chromosomal DNA, mitochondrial DNA, nucleosomes, HMGB-1, and heat shock proteins, which are important promoters of coagulation and have the potential to induce DIC formation." (PMID 38213768, 2024). "HMGB1 not only participates in infectious inflammation (such as sepsis), but also involves in sterile inflammation (such as strokes, acute myocardial infarction)." (PMID 38469295, 2024). "Strategies to inhibit HMGB1, such as the use of neutralizing antibodies or small molecules that interfere with its release or activity, could potentially improve outcomes in patients with sepsis by reducing the hypercoagulable state and associated organ damage." (PMID 39445002, 2024). "In macrophages during polymicrobial sepsis, lactate was found to catalyze lactylation and acetylation of high-mobility group box-1 (HMGB1)." (PMID 38315203, 2024). "Studies have found that HMGB1 can undergo lactylation and acetylation, participating in sepsis development." (PMID 39234245, 2024). "Targeting HMGB1 represents a promising treatment approach for sepsis given its central role in inflammation and immune dysregulation." (PMID 38474222, 2024). "Given these multifaceted roles, HMGB1 represents an important therapeutic target for interventions aimed at modulating the complement system and treating sepsis." (PMID 39445002, 2024). "HMGB1 is a reliable predictor of poor prognosis in sepsis patients, and its downregulation has been shown to alleviate ALI in septic mice." (PMID 38837857, 2024). "The wet/dry ratio, a marker of lung edema, was significantly elevated in sepsis mice but was effectively reduced by Ad‐sh‐HMGB1 administration." (PMID 38837857, 2024). "Further to this, HMGB1 is an extracellular molecule that triggers inflammatory responses under conditions such as sepsis and myocardial infarction and carries out its biological role through its receptor TLR4." (PMID 38256928, 2024). "Lipopolysaccharide (LPS) is a glycolipid that is used to induce vascular damage in both in vivo and in vitro studies, whereas HMGB1 is a significant factor in sepsis and remains stable at high levels for up to 1–1.5 days in animal models." (PMID 38474222, 2024). "This study aimed to investigate the impact of HMGB1 on ferroptosis and its molecular mechanism in sepsis‐induced acute lung injury (ALI)." (PMID 38837857, 2024). "Previous research has shown that the CircTLK1–miR-106a-5p/HMGB1 axis plays an anti-inflammatory role in LPS-stimulated HK-2 cells and is effective in treating a cecum ligation and puncture) sepsis mouse model." (PMID 38705396, 2024). "Remarkably, using a PKM2 inhibitor like picrotoxin can diminish HMGB1 levels, offering protection from sepsis." (PMID 38312312, 2024). "Modified HMGB1, with lactation/acetylation, is released from macrophages via exosomes, contributing to sepsis progression." (PMID 38812044, 2024). "Taken together, these findings highlight the role of HMGB1 deletion in activating Nrf2 signaling and mitigating inflammation in a murine model of sepsis." (PMID 38837857, 2024). "Patients with severe sepsis and experimental animals with sepsis-induced organ dysfunction have elevated HMGB-1 levels in their system." (PMID 39416736, 2024). "In our experiment, we also found that severe sepsis in rats is in direct proportion to the HMGB1 expression, which became weakened after treatment with remazolam." (PMID 38646480, 2024). "The proinflammatory properties of high‐mobility group box protein 1 (HMGB1) in sepsis have been extensively studied." (PMID 38837857, 2024). "Reports suggest that under sepsis conditions, there is an increase in lactylated HMGB1, which is secreted by macrophages via exosomes, thereby enhancing endothelial cell permeability." (PMID 39712019, 2024).
Sepsis (continued). "Previous studies have found that platelets can release a large amount of endogenous HMGB1 during the development of sepsis, which further leads to platelet aggregation and activation and plays a protective role in the body." (PMID 39445002, 2024). "Collectively, these findings suggested that the downregulation of HMGB1 exerts protective effects against sepsis‐induced lung injury, mitigating ferroptosis and oxidative stress during the CLP‐induced lung injury process." (PMID 38837857, 2024). "In animal models of ALI, the inhibition of high-mobility group box 1 (HMGB1), which has been shown to promote NETs release, alleviates sepsis-induced ARDS." (PMID 39170960, 2024). "CGA inhibits the systemic accumulation of high-mobility group box 1 (HMGB-1) and prevents sepsis-induced mortality." (PMID 38612964, 2024). "In sepsis, the release of HMGB1 into the bloodstream by immune cells mediates the activation of caspase‐11 and GSDMD, leading to a hypercoagulable state, the induction of DIC, and resulting in multiple organ failure." (PMID 39445002, 2024). "HMGB-1 inhibition prevents multiple organ failure and increases survival rates in patients with severe sepsis." (PMID 39416736, 2024). "We also found that HMGB1 increased significantly in sepsis model mice and decreased significantly after hydrogen treatment." (PMID 36836478, 2023). "In vivo, the recombinant A-box, but also caspase-1 cleavage of HMGB1 have been shown to be protective against sepsis, a property depending on RAGE." (PMID 37180096, 2023). "In septic patients, the serum HMGB1 was significantly higher than in healthy participants and can persist up to 10 days after sepsis diagnosis." (PMID 36865384, 2023). "HMGB1 is not only an early inflammation mediator but also plays an important role as a late mediator of lethal sepsis." (PMID 35960478, 2023). "Third, HMGB1 elevation has been reported in many types of injuries, such as severe trauma, hemorrhage, lipopolysaccharide (LPS) stimulation, and sepsis." (PMID 37520569, 2023). "HMGB1 can be released in tissue damage and can reflect the severity of sepsis, e.g., the destruction of ileal villi in Salmonella-infected minipigs, and released HMGB1 can emphasize an inflammatory reaction through its cytokine activity." (PMID 38003758, 2023). "HMGB1’s extracellular inflammatory activity in sepsis was first identified in 1999 by administering the bacterial endotoxin (lipopolysaccharide, LPS) in vitro and in vivo models." (PMID 36865384, 2023). "In animal models of endotoxemia and sepsis, passive immunization with HMGB1-neutralizing antibodies prevents organ damage." (PMID 37628850, 2023). "In AI, HMGB1 disrupts the signal transduction of erythropoietin (EPO), causing prolonged anemia after sepsis recovery." (PMID 37223096, 2023). "β-blockers can down-regulate inflammatory mediators (e.g., TNF-α, IL-6, HMGB-1) in animal models of sepsis to reduce the inflammatory response as well as inhibit cardiomyocyte apoptosis." (PMID 37964887, 2023). "In a recent study, we demonstrate that a non-anticoagulant octadecasaccharide (18-mer) can be used as a multi-target therapy in LPS and CLP sepsis murine models by modulating pro-inflammatory extracellular H3, HMGB1, and anti-inflammatory ApoA-I." (PMID 36865384, 2023). "Strategies that target HMGB1 through the use of molecular inhibitors or by inhibiting HMGB1 signaling pathways have been shown to be effective in reducing mortality in sepsis models and altering early cytokine profiles to patterns observed in survivors." (PMID 37048161, 2023). "Specificity protein-1 was found to promote histone deacetylase 4-mediated deacetylation of HMGB1, thereby reducing intestinal barrier dysfunction, oxidative stress, and the inflammatory response induced by sepsis." (PMID 37841247, 2023). "It has been reported that HMGB1 plays an important role in numerous acute and chronic inflammatory diseases, such as sepsis, trauma, and ischemia reperfusion injury." (PMID 37158301, 2023).
Sepsis (continued). "Internalization of HMGB1–haptoglobin complexes by macrophages induces the expression of anti-inflammatory proteins such as heme oxygenase-1 and IL-10, protecting against sepsis-induced lethality." (PMID 37048161, 2023). "Nevertheless, there remain rare relatively studies regarding the role of miR-22 and HMGB1 in sepsis-related AKI." (PMID 35960478, 2023). "Lactate in circulating is the key regulator of HMGB1 secreted by Mφs, and the increase of neonatal lactate levels and the occurrence of sepsis are closely related to the mortality and prognosis of NEC." (PMID 37841247, 2023). "SII, IL-35 and HMGB-1 are remarkably correlated with the severity and prognosis of patients with sepsis." (PMID 36950402, 2023). "In both experimental sepsis models and in sepsis patients, the levels of HMGB1 in the plasma are markedly increased, which positively correlates with disease severity." (PMID 36855150, 2023). "The proinflammatory activity of HMGB1 in sepsis can be attributed directly to its binding to receptors such as the Receptor for Advanced Glycation End-products (RAGE) and Toll-like Receptor 4 (TLR4)." (PMID 36865384, 2023). "The extracellular HMGB1 secreted passively by oxidative stressed cells or actively by activated innate immune cells is highly pro-inflammatory, with a crucial role in sepsis." (PMID 37764336, 2023). "In an animal model of SAE, the serum levels of HMGB1 are increased in sepsis survivors, which remains elevated for at least 4 weeks after CLP." (PMID 36906561, 2023). "In the present study, we were inspired by a recent report elucidating that HMGB1 accumulated in macrophages and was secreted into the extracellular environment in sepsis." (PMID 36709284, 2023). "IL-6 and HMGB1 plasma concentrations at T0 were highest in the septic group, but from T1 until T2, the sepsis-induced MODS group of patients presented the highest concentrations." (PMID 37441100, 2023). "In 1999, HMGB1 was first reported to participate in the pathogenesis of sepsis as a new potential late-stage inflammatory mediator, which led researchers to recognize the significance of HMGB1 as an inflammatory factor." (PMID 37559147, 2023). "Antibody drugs currently used in clinical trials or laboratory studies on sepsis include anti-HMGB1 antibodies, atezolizumab, adrecizumab, and tocilizumab." (PMID 37629199, 2023). "For example, we recently reported the involvement of NAD+/SIRT1 in the modulation of HMGB1 during sepsis." (PMID 38057866, 2023). "In other murine models and clinical cases of sepsis, the serum upregulation of IL-6, TNFα, and HMGB1 was observed." (PMID 37569277, 2023). "Correlation analysis between the levels of SII, IL-35, HMGB-1 and the prognosis of patients with sepsis." (PMID 36950402, 2023). "N-acetyl heparin has been referred to as non-anticoagulant heparins (NAH) in many studies, shown to protect against sepsis-induced lethality and organ damage by targeting HMGB1/LPS complex, heparanase, and histones." (PMID 36865384, 2023). "Rare ginsenosides Rk1 and Rg5 have an inhibitory effect on high mobility group box 1 (HMGB1)-mediated sepsis." (PMID 36817458, 2023). "HMGB1’s role in the progression of chronic inflammatory diseases, including rheumatoid arthritis, cardiovascular disease, sepsis, and cancer, has been well-documented." (PMID 38139865, 2023). "A recent study from our group also indicated that the interaction between HMGB1 and extracellular histone 3 (H3) is HS size and sulfation pattern dependent in sepsis by applying a synthetic HS oligosaccharide library." (PMID 36865384, 2023). "Extracellular HMGB1 functions as a proinflammatory molecule, and its passive or active release from cells can result in numerous inflammatory diseases, such as sepsis." (PMID 38026444, 2023). "Among the numerous mediators in sepsis, the high mobility group box 1 (HMGB1) is an endogenous DAMP that mediates downstream effects within the inflammatory cascade." (PMID 36741234, 2023).
Sepsis (continued). "It is well known that the proinflammatory cytokine HMGB1 plays an important role in the pathogenesis of sepsis." (PMID 36836478, 2023). "Relative to the sham group, the miR-22 mRNA expression was notably down-regulated (p < 0.01), while the HMGB1 mRNA and protein expression were obviously up-regulated in the sepsis group (p < 0.01)." (PMID 35960478, 2023). "Inhalation of 2% H2 also attenuated severe sepsis-induced intestinal injury by modulating HO-1 and HMGB1 release in mice." (PMID 38136182, 2023). "Most research on the Warburg effect and sepsis focused on overcoming the Warburg effect and reducing the expression of HMGB1 (high mobility group protein) by agents including celastrol, shikonin, and capsaicin, which inhibit the PKM2-mediated Warburg effect." (PMID 37434129, 2023). "The protective effects of annexin A5 in the sepsis models are mediated in part by inhibiting LPS and high-mobility group box-1 (HMGB1) binding to the TLR4/MD2 complex." (PMID 38269269, 2023). "Several studies have investigated HSs’ anti-HMGB1 activity in sepsis with various heparins and synthetic HSs." (PMID 36865384, 2023). "Another mechanism involves HMGB1 (high-mobility group box protein 1), a DAMPs that is increased in patients with sepsis or trauma and also in animals treated with LPS." (PMID 36835934, 2023). "This review describes inflammatory cascades implicating HMGB1 and strategies for its use to mitigate sepsis-induced encephalopathy." (PMID 37048161, 2023). "As a late‐phase alarmin in sepsis, HMGB1 interacts with RAGE to deliver cytosolic LPS, consequently activating the NLRP3 inflammasome in murine macrophages and lung ECs, leading to caspase‐11‐dependent pyroptosis." (PMID 38020710, 2023). "HMGB1 carried by platelet-derived sEVs promotes the formation of neutrophil extracellular traps in sepsis and subsequent organ damage, and its inhibition in sepsis increases the survival rate." (PMID 37998605, 2023). "As reported in sepsis, DAMPs like high mobility group protein B1 (HMGB1) and mitochondrial DNA (mtDNA) are potent inducers of type I interferons, which negatively regulate emergency hematopoiesis." (PMID 37223096, 2023). "It has been reported that circulating HMGB1 has an important effect on the severity and mortality of sepsis." (PMID 38026444, 2023). "HMGB-1 is the most extensively studied DAMPs that drives tissue injury during ARDS or sepsis; results from our animal study demonstrated that the inhibition of HMGB-1 efficiently attenuates disease progression." (PMID 36507222, 2023). "The levels of SII, IL-35 and HMGB-1 in different groups were compared, and their correlation with the severity and prognosis of sepsis was analyzed." (PMID 36950402, 2023). "In lipopolysaccharide (LPS)-induced endotoxemia and sepsis, HMGB1 is an extracellularly released mediator in both inflammatory and repair responses." (PMID 37628850, 2023). "Intriguingly, we found that in macrophages during sepsis, lactylation of HMGB1 mediates its exosomal secretion." (PMID 37441587, 2023). "HSBPs, such as HMGB1 and histones, have been recognized as crucial modulators for inflammation and coagulation in sepsis." (PMID 36865384, 2023). "Hmgb1 is not only a nuclear factor that enhances transcription but also an important cytokine that mediates the pathological effects of cancers, sepsis and other diseases." (PMID 37315292, 2023). "High mobility group box 1 protein (HMGB1), a nuclear protein, plays a vital role in the late immune response to sepsis." (PMID 36774341, 2023). "Intriguingly, we have demonstrated that in macrophages during sepsis, HMGB1 is secreted in exosomes after its lactylation." (PMID 37441587, 2023). "In the LPS/GalN model of sepsis, RvD1 administration significantly reduced high mobility group box-1 (HMGB1), TNF-, IL-6 and macrophage chemotactic protein – 1 (MCP-1) in parallel to a decreased neutrophil recruitment." (PMID 35432367, 2022).